CRP (C-reactive protein)
Diseases named in the same sentence as CRP in open-access papers (continued):
Sharing a sentence is not in itself a finding about the gene and the disease.
cancer (continued). "However, the presurgical CRP level did not correlate with tumor differentiation: 33.3% of all patients with CRP >15 and 25.0% of those with CRP ≤15 mg/l presented with poorly differentiated (≥G3) cancer (p=0.53)." (PMID 23642165, 2013). "Elevated plasma CRP levels are also associated with an increased risk of cancer, but causality has not been established." (PMID 23642165, 2013). "By contrast, the study indicated that high sensitivity C-reactive protein was independently associated with cardiovascular mortality but not with cancer mortality in men." (PMID 23984981, 2013). "For example, increases in CRP concentrations have been associated with poorer prognosis of survival in cancer patients, particularly with advance disease independent of tumor stage." (PMID 23947403, 2013). "IVC therapy appears to reduce CRP levels in cancer patients." (PMID 23947403, 2013). "YKL-40 and C-reactive protein (CRP) are biomarkers that may reflect cancer-related subclinical inflammation." (PMID 22095223, 2012). "Although we cannot evaluate the aetiological aspects of an association between CRP, YKL-40, and cancer risk in this observational cohort study of the general population, several biological mechanisms may account for the observed associations." (PMID 22095223, 2012). "Presently, it is unknown whether CRP and YKL-40 potentially could complement each other in cancer risk prediction." (PMID 22095223, 2012). "Furthermore, blood levels of the inflammatory marker C-reactive protein (CRP) were available from routine hospital analysis of cancer patients." (PMID 22973451, 2012). "The biologic underlying mechanisms of the relationship between CRP levels and increased cancer risk are not yet definite." (PMID 22912790, 2012). "However, whereas CRP is produced in the liver, YKL-40 is produced at the site of pathology by different cells, including cancer cells and cancer-associated macrophages." (PMID 22095223, 2012). "While these data indicated that elevated CRP per se was unlikely to be a cause of cancer, they did identify CRP as an important prognostic biomarker of outcome that revealed an underlying inflammatory process associated with high SUA levels." (PMID 23369448, 2012). "Thus, CRP is produced in the liver, whereas YKL-40 is produced at the site of pathology by different cells, including cancer cells and cancer-associated macrophages." (PMID 22095223, 2012). "In this observational cohort study of the general population, we did not seek to evaluate the aetiological aspects of an association between CRP, YKL-40, and cancer risk, but rather considered CRP and YKL-40 as biomarkers reflecting cancer-related subclinical inflammation." (PMID 22095223, 2012). "CRP is frequently used as a marker for inflammation, but may also serve as prognostic tool in cancer patients." (PMID 22216763, 2012). "This means that elevated CRP levels are a risk predictor for any cancer, independent of YKL-40 levels." (PMID 22095223, 2012). "While CRP is mostly known as a sensitive inflammatory marker indicating systemic response to pathogens, its prognostic potential has been recently investigated in a subset of cancers." (PMID 22811589, 2012). "Additionally, in case of other malignancies, CRP had been found to inhibit apoptosis of carcinoma cells, thereby directly regulating tumor cell growth and survival." (PMID 22857740, 2012). "If serum CRP is taken as a proxy measure of systemic inflammation due to cancer cachexia, this indicates that weight loss in cancer is not merely due to reduced calorie intake." (PMID 21760776, 2011). "Recently, the presence of a systemic inflammatory response, as evidenced by an elevated C-reactive protein concentration sampled incidentally in a large hospital-based cohort, was associated with a shorter duration of cancer and non-cancer survival." (PMID 20717110, 2010). "C-reactive protein (CRP) is gaining credibility as a prognostic factor in different cancers." (PMID 20234363, 2010).
cancer (continued). "The median levels of CRP increased with increasing stage, and we also noted significant differences between the CRP level and cancer stage (the median level of CRP in stage I 0.06 ± 0.29 mg/dl, stage II 0.07 ± 0.15 mg/dl, stage III 0.12 ± 0.30 mg/dl and stage IV 0.39 ± 0.50 mg/dl; P < 0.001)." (PMID 19457231, 2009). "Thus, it has been reported that serum CRP levels are higher in cases of invasive cancer than in cases of non-invasive cancer." (PMID 19457231, 2009). "Indeed most of the selected markers provide little classification value for cancer status when considered alone as individual markers with only CA-125 and C-reactive protein having appreciable classification potential." (PMID 19240799, 2009). "Preoperative serum IL-6 and CRP levels were related to cancer stage and might be markers of tumor invasion, LN metastasis and TNM stage." (PMID 19457231, 2009). "The observations might explain some of the clinical fluctuations in cancer growth and immune response activity, which is what led us to study more frequent measurement of CRP initially." (PMID 19948067, 2009). "In another study of elderly people, an association between CRP haplotype B, bearing the +1846 A-allele, and cancer-related death was found, but the cancer cases were not analysed separately according to site." (PMID 19436291, 2009). "On univariate analysis, stratified by stage, increased Ki-67 labelling index (P<0.05), increased COX-2 expression (P<0.05), C-reactive protein (P<0.05) and no adjuvant therapy (P<0.01) were associated with poorer cancer-specific survival." (PMID 17024120, 2006). "On multivariate analysis with sex, UISS and C-reactive protein entered as covariates, only UISS (HR 2.70, 95% CI 1.00–7.30, P=0.050) and C-reactive protein (HR 4.00, 95% CI 1.21–13.31, P=0.024) were significant independent predictors of cancer-specific survival." (PMID 16523196, 2006). "The results of the present study indicate that in patients selected to undergo potentially curative resection for gastro-oesophageal cancer, the presence of an elevated preoperative C-reactive protein concentration is an independent predictor of poor cancer-specific survival." (PMID 16685271, 2006). "In the cancer patients who had detectable circulating preoperative C-reactive protein concentrations (n=41), log-transformed concentrations of C-reactive protein were significantly correlated with interleukin-6 (r2=0.62, P<0.001) and interleukin-10 (r2=0.33, P<0.001)." (PMID 17003778, 2006). "On multivariate analysis, only the positive to total lymph node ratio (hazard ratio (HR) 2.02, 95% confidence interval (CI) 1.44–2.84, P<0.001) and preoperative C-reactive protein concentration (HR 3.53, 95% CI 1.88–6.64, P<0.001) were independent predictors of cancer-specific survival." (PMID 16685271, 2006). "Those patients with an elevated preoperative C-reactive protein concentration (>10 mg l−1) had a mean cancer-specific survival of 71 months compared with 96 months (P<0.001) in those patients with a C-reactive protein concentration in the normal range (⩽10 mg l−1)." (PMID 16523196, 2006). "There is increasing evidence that the presence of a systemic inflammatory response, as evidenced by elevated concentrations of C-reactive protein, is a prognostic factor independent of stage, performance status and weight loss in patients with advanced cancer." (PMID 16479253, 2006). "In the cancer patients who had detectable circulating postoperative C-reactive protein concentrations (n=35), log-transformed concentrations of C-reactive protein were significantly correlated with those of interleukin-6 (r2=0.66, P<0.001) and interleukin-10 (r2=0.33, P<0.001)." (PMID 17003778, 2006). "Glasgow Prognostic score may thus reflect both the presence of an ongoing systemic inflammatory response (C-reactive protein) and the progressive nutritional decline (albumin) of the patient with advanced cancer." (PMID 16479253, 2006).
cancer (continued). "The aim of the present study was to examine the relationship between clinico-pathological status, C-reactive protein concentration, measured before surgery, and cancer-specific survival in patients selected for potentially curative resection of gastro-oesophageal cancer." (PMID 16685271, 2006). "Furthermore, both a low tumour CD4+ T-lymphocyte infiltration and an elevated C-reactive protein predict poor cancer-specific survival." (PMID 15700032, 2005). "Those patients with an elevated preoperative C-reactive protein concentration (>10 mg l−1) had a mean cancer-specific survival of 65.5 months (95% CI 46.8–84.2) compared with 103.7 months (95% CI 81.8–125.6) in those patients with a C-reactive protein concentration in the normal range (⩽10 mg l−1)." (PMID 15726119, 2005). "Proteolysis-inducing factor has also been shown to activate NF-κB in primary hepatocytes and the human cancer cell line HepG2, resulting in the increased production of interleukin-6 and -8 (IL-6 and IL-8) and C-reactive protein and the decreased production of transferrin." (PMID 15714207, 2005). "In the cancer patients neither sIL-6R nor sgp130 concentrations were significantly associated with either IL-6 or C-reactive protein concentrations." (PMID 15570310, 2004). "When the cancer patients were divided into control (⩽10 mg l−1) and acute-phase response (>10 mg l−1) groups based on the upper normal limit of serum CRP, those in the acute-phase group had an average 30% reduction in drug metabolism (0.070±0.024 vs 0.049±0.022 min−1, respectively)." (PMID 12177794, 2002). "In addition to D dimer, CRP might serve as a potential biomarker for cancer-related strokes, but further clinical confirmation is needed." (PMID 39857281, 2025). "Although the hematological results suggest an increase in WBC, which could indicate systemic inflammation, the lack of elevated levels of albumin, CRP, and IL-6 suggests that cancer did not cause systemic inflammation." (PMID 40284805, 2025). "Also, in our study, cancer patients with FN had significantly higher blood level of CRP and procalcitonin compared to the other groups (56.45 mg/dl versus 5.6 mg/dl and 3.0 mg/dl respectively for CRP and 0.44ng/dl versus 0.09ng/dl and 0.06 ng/dl respectively for procalcitonin." (PMID 40369641, 2025). "In humans, a recent cross-sectional observational study enrolling 624 adults in the American Cancer Society’s Cancer Prevention Study-3 Diet Assessment Substudy found a positive association between the consumption of artificial NNSs, including ASP, SAC, SUC, and Ace-K, and leptin, CRP, and IL-6." (PMID 41156503, 2025). "Similarly, CRP, a general marker of inflammation, has been linked to cardiovascular disease, cancer risk, lung damage, and recurrent infections in non-TB studies." (PMID 40475250, 2025). "CRP may be a diagnostic and prognostic index for cancer, an acute-phase protein that is not specific to cancer type." (PMID 40558585, 2025). "Elevated preoperative CRP levels may also reflect advanced cancer stages." (PMID 41439853, 2025). "A 2022 prospective cohort study by Japan’s National Cancer Center demonstrated that COX-2, as a mechanistic inflammatory biomarker, enhances risk stratification for tumor initiation when integrated with traditional markers like CRP, providing incremental value beyond standalone CRP assessment." (PMID 40563367, 2025). "Finally, given the immunologic aspects of cancer and major surgery, research into how patient-specific factors (like baseline inflammatory status, use of steroids or immunosuppressants, and tumor-related inflammation) modulate CRP responses would be valuable." (PMID 41153812, 2025). "This could suggest systemic effects of cancer treatments or cancer itself on CRP levels." (PMID 41419753, 2025). "Furthermore, no reports have shown whether the clinical implications of serum CRP levels vary with life expectancy in patients with advanced cancer." (PMID 41302347, 2025).
cancer (continued). "Whether CRP has similar upregulating effects on glycoprotein and MMP expression and activity in the context of cancer remains poorly understood; thus, the role of CRP in ECM remodeling in tumor cells as well as other cell types within the TME will require rigorous evaluation." (PMID 41614767, 2025). "CRP release is stimulated by IL-6, which also controls stromal desmoplasia, encourages tumor-induced immunosuppression and angiogenesis, suppresses apoptosis, increases the proliferation of cancer cells, and aids in metastasis, including the creation of a pro-metastatic niche in the liver." (PMID 40842988, 2025). "Hence, cancer patients with high CRP level maybe need for timely computer tomography examination and more aggressive treatment." (PMID 38215120, 2024). "A serum CRP value of 5 mg/dL may be a useful indicator for initiating cancer cachexia care." (PMID 39765960, 2024). "CRP may indirectly influence tumor growth and metastasis by affecting the tumor microenvironment, modulating immune responses, and influencing the behavior of cancer cells." (PMID 38474160, 2024). "CRP was found to have the highest area under the curve as an individual marker (0.76 [95% confidence interval {CI} = 0.73–0.79) with 71% sensitivity and 80.5% specificity for cancer within 6 months of first presentation of UWL in primary care followed by raised neutrophils (0.64 [CI = 0.61–0.67])." (PMID 39054298, 2024). "CRP is a nonspecific inflammatory marker that rapidly elevates in inflammatory responses and has been linked to an increased risk of cardiovascular disease and cancer." (PMID 38281018, 2024). "Therefore, this CRP value may be a clinically critical point for the initiation of multimodal care for patients and family caregivers affected by cancer cachexia in supportive and palliative care." (PMID 39765960, 2024). "In the context of cancer, CRP levels may also be elevated, making it a potential cancer biomarker." (PMID 39687887, 2024). "Thus, CAR, which combines CRP and Alb, may be a prognostic indicator for patients with cancer, and high CAR levels could be a marker of poor overall survival." (PMID 38913646, 2024). "Studies have shown significant reductions in inflammatory markers such as C-reactive protein (CRP), tumor necrosis factor-alpha (TNF-α), and interleukin-6 (IL-6) among individuals adhering to the MD, suggesting its pivotal role in mitigating chronic inflammation-associated with cancer development." (PMID 38773621, 2024). "In line with our previous work, focusing on why cancer patients with elevated blood CRP levels have inferior outcomes, the hypothesis evolved that the potent monomeric/modified form of CRP may play a direct pro-inflammatory role within the TME of systemically inflamed cancer patients." (PMID 37006231, 2023). "The findings indicate that changes in CRP during the very early postoperative period, specifically between postoperative days 2 to 3, may be the most reliable positive indicator of AL following esophagectomy for cancer." (PMID 37964057, 2023). "Furthermore, accumulating evidence has shown that nutritional and immune status, represented by the prognostic nutritional index (PNI), serum albumin, CRP, and body mass index (BMI), play a role in the development and progression of malignant tumors, which in turn affects survival." (PMID 36831069, 2023). "CRP may be useful to indicate whether further diagnostic evaluation is needed when patients present with nonspecific signs and symptoms of cancer." (PMID 36440611, 2023). "ESR and CRP were both observed to be associated with advanced stages and worse ECOG status in our study, verifying the ability of these inflammatory parameters as biomarkers to indicate cancer severity; this may, thus, help clinicians make clinical decisions." (PMID 37346066, 2023). "Furthermore, lymphocyte–CRP and CRP–albumin ratios are prognostic predictors for many cancers." (PMID 37794336, 2023).
cancer (continued). "Furthermore, changes in CAR, composed of CRP and albumin, may be more sensitive to patient and/or cancer conditions than CRP or albumin alone." (PMID 37333829, 2023). "Furthermore, transwell invasion assays were performed in all cell lines to evaluate the impact of CRP on cancer cell invasiveness, and exogenous CRP could significantly promote cell invasiveness." (PMID 37929799, 2023). "The Glasgow Prognostic Score (GPS), which combines C-reactive protein and albumin levels that reflects the systemic inflammation status and the nutrition status of the patient, respectively, has been reported to be a reliable tool for assessing the status of cancer cachexia." (PMID 36674837, 2023). "Despite the reduction of CRP levels observed following IMDC treatment, this finding might be nonspecific and potentially confounded by concurrent clinical factors, such as underlying malignancy, other inflammatory processes, and systemic anti-cancer therapy." (PMID 37476185, 2023). "Similarly, the Glasgow Prognostic Score (GPS) based on CRP and albumin levels might be a useful indicator of performance status and survival in cancer patients." (PMID 37816885, 2023). "In cancer patients, nutritional status deteriorates with progression due to inadequate nutrient intake and tumor overconsumption, resulting in hypoalbuminemia that stimulates various inflammatory cytokines, including interleukin 6, thus promoting CRP production in the liver." (PMID 37333829, 2023). "We found that elevated CRP level at the time of MPMs diagnosis could predict VTE (p = .036) but not VTE mortality (p = .457) though literature identifies elevated CRP as a predictor of early mortality in cancer patients." (PMID 36314077, 2023). "Moreover, higher CRP can possibly show drug resistance in cancer cases." (PMID 37873776, 2023). "Therefore, serum CRP and albumin are considered as interrelated serum biomarkers that may reflect host and cancer status, respectively." (PMID 37333829, 2023). "In addition, significant changes in other readily accessible inflammatory markers comprising acute phase reactants, primarily as low serum albumin level and increased serum globulins and C-reactive protein (CRP), were observed as a result of cancer-associated inflammation." (PMID 36983756, 2023). "Moreover, another observational study in UKB suggested different patterns of nonlinear associations between C-reactive protein (potential mediator) and cancer sites such as the kidney." (PMID 37424008, 2023). "In addition, there is evidence that cancer cells can increase the production of inflammatory proteins from infiltrating macrophages, which may explain the high concentration of CRP in cancer patients." (PMID 37083267, 2023). "Therefore, CRP alone cannot identify patients with cancer, but when elevated, it may be used to indicate whether further diagnostic evaluation is needed in patients with nonspecific signs and symptoms of cancer." (PMID 36440611, 2023). "When there is acute rejection, bacterial infection, and operation, the synthesis of CRP in hepatocytes is significantly increased, it can activate complement, participate in apoptosis, promote granulocyte and macrophage phagocytosis, and can predict or diagnose malignant tumors." (PMID 37081512, 2023). "Indeed, epidemiologic data suggest that elevated levels of CRP, when measured by high-sensitivity assays, are not merely a marker of prevalent cancer, but are also associated with an increased risk of future cancer in apparently healthy individuals." (PMID 35223501, 2022). "Moreover, a high C-reactive protein (CRP)/albumin (ALB) ratio (CAR) was found to be associated with poor outcome of cancer patients, and this marker could be used as a predictor of poor cancer prognosis." (PMID 35372394, 2022).